MMP9 (matrix metallopeptidase 9)
Diseases named in the same sentence as MMP9 in open-access papers (continued):
Sharing a sentence is not in itself a finding about the gene and the disease.
prostate carcinoma (continued). "PL was found to significantly inhibit the activation of NF-κB and modulate the expressions of NF-κB mediated proteins such as IL-6, IL-8, MMP-9, and intercellular adhesion molecule 1 (ICAM-1), thereby suppressing the metastatic potential of the prostate cancer cells." (PMID 36046754, 2021). "Multiple angiogenic factors are over-expressed in highly metastatic prostate cancer cell lines, including VEGF, ICAM-1, IL-8 and TGF-β2 and expression of factors such as VEGF and ICAM-1 may be dependent on MMP-9 expression." (PMID 33805598, 2021). "Consistent with previous observations, we demonstrated that ZKSCAN3 silencing in prostate cancer lines resulted in significant reduction of cell viability, colony formation, cell migration, cell invasion, and the expression of MMP2/MMP9, as well as significant induction of apoptosis." (PMID 32824199, 2020). "Employing siRNA-based partial target modulation in DU145 and PC3 prostate carcinoma cells, inhibition of EMT-related gene expression (with downregulation of MMP9, MMP2, VIM, and SNAI1, among others) and suppression of migration and metastasis were assessed in vitro." (PMID 32466621, 2020). "As has been reported, the intracellular domain (ICD) of CD44 interacting with RUNX2 to form a co-transcription factor drives the migration of prostate cancer cell line PC3 through upregulating the levels of metastasis-related genes, such as matrix metalloproteinase 9 (MMP9) and osteopontin." (PMID 33303029, 2020). "Our results showed that TROAP knockdown could suppress prostate cancer cell migration and invasion by inhibiting TWIST and MMP-9 expressions." (PMID 33692939, 2020). "During prostate cancer progression the level of enzymes involved in metastasis, uPA, MMP-2, and MMP-9, displayed increased levels in the dorsolateral prostate of TRAMP mice, but the intake of apigenin downregulated their levels, which led to a “complete absence” of the metastasis." (PMID 30823649, 2019). "Consistently, the radial repositioning patterns of FLI1, MMP9 and MMP2 also do not correlate with the risk/aggressiveness of prostate cancer." (PMID 31681438, 2019). "Another study has indicated that mast cells promote the growth of cancer in the initial stages not later stages of prostate cancer by producing MMP-9 in ECM." (PMID 31579438, 2019). "MMP-9 expression correlates with CRPC progression and increased prostate cancer aggression." (PMID 31836808, 2019). "In conclusion, the downregulation of HDGF significantly is associated with the inhibition of the migration and invasion in prostate cancer cells, at least in part, by suppressing EMT process and the expression of MMP9 and MMP2, which play an important role in the tumorigenesis of PCa." (PMID 29300772, 2018). "Furthermore, IL-6 from prostate carcinoma cells generates a CAF phenotype and leads to increased MMP2 and MMP9 levels in fibroblasts." (PMID 30356678, 2018). "The binding of extracellular S100A4 to embigin mediates prostate cancer progression by orchestrating multiple mechanisms including inhibition of AMPK activity, activation of NF-κB, MMP9, and mTORC1 signaling, and inhibition of autophagy, which lead to an increase in cellular motility." (PMID 30041429, 2018). "It has reported that MMP-9, rather than MMP-1 polymorphism variants were associated with pathological parameters in predicting the clinical outcome of prostate cancer patients." (PMID 28445160, 2017). "MMP-2 and MMP-9 destroy ECM and help breast and prostate cancer cells migrate to new places." (PMID 29062841, 2017). "Regardless of the T cell / prostate cancer mechanism, MMP9 expression by osteoclasts was also not modulated by FGF11." (PMID 28097375, 2017). "Moreover, the results showed that inhibition of the ERK pathway decreased the expression of MMP9 in prostate cancer cells, suggesting that the ERK pathway is involved in AQP9-mediated MMP9 expression in prostate cancer cells." (PMID 27187384, 2016).
prostate carcinoma (continued). "In addition, using a prostate cancer model, CXCR4-dependent migration was shown to increase matrix metalloproteinase-9 (MMP-9) expression and decrease TIMP metallopeptidase inhibitor 2 (TIMP2) expression, contributing to a more invasive phenotype." (PMID 27618899, 2016). "The prostate cancer C4-2 cell line was incubated with increasing concentrations of oxLDL (25, 50, 100 μg/mL) during 12 hours, and the expression of the pro-angiogenic markers VEGF, MMP-2 and MMP-9 was analyzed using real-time PCR." (PMID 25170920, 2014). "We also confirm, using the aortic ring assay and the chicken embryo CAM xenograft model, that the increase of VEGF, MMP-2 and MMP-9 expression mediated by LOX-1/oxLDL has a tumoral angiogenic effect both in vivo and ex vivo on C4-2 prostate cancer cells models." (PMID 25170920, 2014). "Several are known biomarkers for diagnosis and prognosis of prostate cancer (APC, GSTP1, KIT, PYCARD, PGDGRB, RARB, RARRES1, and TIMP1) and some though not biomarkers, were found to be dysregulated in the disease (CDKN1B, MMP7, and MMP9)." (PMID 24626295, 2014). "The prostate cancer cells models C4-2/LOX-1(−) and C4-2/LOX-1(+) were incubated with 100 μg/mL oxLDL during 12 hours, and expression of the pro-angiogenic markers (VEGF, MMP-2 and, MMP-9) was analyzed." (PMID 25170920, 2014). "However, in vitro studies showed that NGAL plays a significant role in the progression of prostate cancer by regulating MMP2 and MMP-9." (PMID 24742531, 2014). "In the present study, we noticed that RUNX3 regulated prostate cancer cell metastasis through MMP-2 but not MMP-9." (PMID 24475196, 2014). "Our results showed that expression of Snail, MMP-2 and MMP-9 but not Slug is up-regulated in the prostate cancer sections derived from PC3 and LAPC-4 cells overexpressing TIMP-1 when compared to the sections derived from the control PC3 and LAPC-4 cells." (PMID 24143225, 2013). "In prostate cancer, RhoC promotes tumor metastasis by sequential activation of Pyk2, focal adhesion kinase (FAK), mitogen-activated protein kinase (MAPK) and Akt, followed by the upregulation of MMP2 and MMP9, resulting in the induction of tumor cell invasion." (PMID 23382905, 2013). "Moreover, luteolin reduced cell viability and induced apoptosis in prostate cancer cells, which were correlated with the downregulation of AKT, ERK, mTOR, P70S6K, MMP-2, and MMP-9 expressions." (PMID 23300633, 2012). "Among them, MMP-2, MMP-9 and MMP-7 play a critical role in prostate cancer progression." (PMID 21629786, 2011). "Other studies using a human prostate cancer cell line (DU-145) or a colorectal cancer cell line (MC-26), treated with 10 and 100 μM NS-398, reported a reduction in the release of pro and active MMP-2 and MMP-9 in the culture media." (PMID 16831226, 2006). "However, depletion of CDC7 in our advanced prostate cancer cell line led to a decrease in TGF-β1, SMAD3, and MMP9 expressions and therefore targeting CDC7 could also be a method to inhibit TGF-β driven metastasis caused by ADT." (PMID 41413594, 2025). "The reduction in Twist1, Snail, and MMP9 expression likely suggests that the cells are undergoing a mesenchymal-to-epithelial transition (MET), which diminishes the mesenchymal migratory and invasive characteristics seen in aggressive PC3 prostate cancer cells." (PMID 38213538, 2023). "In in vitro tests using prostate cancer cell lines, the BTK inhibitor ibrutinib was found to drastically reduce prostate cancer cell proliferation, wound healing, migration, and invasion, as well as block tumor cell matrix metalloproteinase-2 (MMP-2) and MMP-9 protein production." (PMID 36903645, 2023). "Furthermore, resveratrol inhibited the migration and invasion of prostate cancer cells by promoting demethylation and increasing the expression of tissue inhibitors of metalloproteinases, TIMP2, and TIMP3 and by suppressing the expression of MMP-2 and MMP-9." (PMID 37446252, 2023).
prostate carcinoma (continued). "In addition to DNA repair pathways, BRCA1/2 also could repress the progression of prostate cancer by inhibiting PI3K/AKT and MAP/ERK pathways, as well as MMP9 and AR signaling." (PMID 35734583, 2022). "Interestingly, the GHRH antagonist MZ-5-516 in prostate cancer cells, as well as MIA-602, MIA-606 and MIA-690 in non-small cell lung cancer cells, reduced VEGF secretion and attenuated the mRNA expression and activity of MMP2 and MMP9." (PMID 36232554, 2022). "This tumor-suppressive role has been suggested to be due to different pathways, including matrix metallopeptidase 9 (MMP-9) and matrix metallopeptidase 13 (MMP-13) down-regulation in lung mucoepidermoid carcinoma, as well as VEGF and MMP-9 downregulation in pancreatic and prostate cancers." (PMID 34439295, 2021). "Western blotting assay further indicated that CCL5 could induce epithelial-mesenchymal transition (EMT) in both prostate cancer cells, characterized by the decreased expression of E-cadherin as well as the increased expression of N-cadherin, Vimentin, MMP2, and MMP9." (PMID 32300100, 2020). "Furthermore, expression of distinct VCA Nbs (VCA Nb7 and VCA Nb14) in PC-3 prostate cancer cells resulted in reduced overall matrix degradation without affecting MMP9 secretion/activation or MT1-MMP localisation at invadopodial membranes." (PMID 28938008, 2017). "Moreover, in prostate cancer cells, RhoC activates matrix metallo‐proteinases 2 and 9 (MMP2 and MMP9) in vitro, which could contribute to invasion." (PMID 25677806, 2015). "Furthermore, we demonstrated miR-195 could inhibit prostate cancer cell motility by regulated the expression of c-Met, MMP1, MMP9." (PMID 26337460, 2015). "In the current study, we did not examine whether MMP-9 also cleaved ICAM-1 in BK-mediated cell motility of prostate cancer cells." (PMID 23803661, 2013). "In addition, siRNA silencing of TRPV2 reduced the growth and invasion of PC-3 cells in xenograft models of prostate cancer and reduced the expression of invasive markers, MMP2, MMP9, and cathepsin-B, suggesting that inhibition of TRPV2 may reduce the aggressive phenotype of prostate cancer." (PMID 32825277, 2020). "In addition, in prostate cancer cells TGF-β1 stimulates the expression and activity of uPA, PAI-1, and MMP-9, resulting in a net increment of pericellular plasminogen activation, increased activation of MMP-9, and finally increased tumour cell invasion and metastasis." (PMID 23766912, 2013). "Therefore, we decided to determine whether or not MMP9 is also positively regulated by SLUG in prostate cancer cells." (PMID 22074556, 2011). "The other prostate cancer DU145 cells, which are malignant similar to PC3, expressed high levels of IRS-2 similar to PC3 but did not secrete MMP-9." (PMID 37894751, 2023). "In the present study, we demonstrated that MMP-2, MMP-9 and MMP-14 are positive in prostate cancer and its regulators are negative in the majority of cases." (PMID 26742965, 2015).
atherosclerosis (347 papers, 2008 to 2026). A disease characterized by the build-up of fatty material and calcium deposition in the arterial wall resulting in partial or complete occlusion of the arterial lumen. "The observed dose-dependent decrease in both MMP-9 transcript levels and enzymatic activity suggests that ganetespib can modulate tissue remodeling processes associated with chronic inflammation and atherosclerosis." (PMID 41155259, 2025). "Increased MMP9 levels have also been associated with the initiation of atherosclerosis, since high serum levels have been associated with lumen stenosis in coronary arteries." (PMID 40564951, 2025). "Dysregulated MMP-9 activity has been implicated in the pathogenesis of diverse conditions, including atherosclerosis, aneurysm formation, chronic obstructive pulmonary disease (COPD), asthma, neurodegeneration, and malignancy." (PMID 41304763, 2025). "Clinically, statin therapy has been associated with lower serum and tissue MMP-9 concentrations in patients with atherosclerosis and post-revascularization, correlating with improved plaque stability and reduced rupture risk." (PMID 41304763, 2025). "MMP9 activity in vascular tissues is associated with age‐related conditions such as atherosclerosis." (PMID 40325911, 2025). "MMP9, a zinc‐dependent endopeptidase, is critical in extracellular matrix remodeling and is implicated in various cardiovascular pathologies, including atherosclerosis, aneurysm formation, and post‐infarction remodeling." (PMID 40151877, 2025). "The level of MMP-9 increases rapidly in cardiovascular diseases such as arterial hypertension, atherosclerosis, and myocardial infarction, and a significant number of publications on MMP-9 emphasise its importance as a useful diagnostic and prognostic marker." (PMID 38540214, 2024). "Although it is known that MMP9 is involved in the progression of plaque and helps predict plaque instability, it is unclear about its role in the early development of atherosclerosis for early risk stratification, especially in patients with diabetes." (PMID 38660518, 2024). "An analysis of MMP‐9 gene polymorphisms found MMP‐9 to have potential clinical significance in the pathogenesis of atherosclerosis." (PMID 39039803, 2024). "Changes in Mmp9 and Mmp3 expression/activity are linked to cardiovascular diseases, including hypertension, lipid disorders, and atherosclerosis." (PMID 38890983, 2024). "Studies found that mice with a deficiency of MMP3 or MMP9 showed reduced macrophage infiltration in atherosclerosis in atherosclerotic plaques." (PMID 37006258, 2023). "MMP-9 was also previously associated with multiple forms of peripheral vascular disease, such as atherosclerosis, critical limb ischemia, intimal hyperplasia and varicose veins." (PMID 37175078, 2023). "In the MMP family, MMP-9 is the member that is most closely associated with vascular lesions, including acute MI, atherosclerosis, heart failure, and aortic aneurysm." (PMID 36159562, 2022). "Matrix metalloproteinase-9 (MMP-9) is a zinc-dependent enzyme involved in the degradation of extracellular matrix and has been linked to vascular remodeling and atherosclerosis, as well as ovarian dysfunction." (PMID 35329952, 2022). "Matrix metalloproteinases-9 (MMP-9) has been implicated in the pathogenesis of several disorders, including tumor metastasis, inflammatory disorders, and atherosclerosis." (PMID 35615376, 2022). "A previous study of the other types of cells besides those implicated in the atherosclerosis process (fibrochondrocytes) demonstrated that E2 mediates MMP-9 overexpression through the activation of the ERα/ERK and NF-κB/ELK-1 signaling pathways." (PMID 36142876, 2022). "MMP-9 is secreted from macrophages in the fibrous cap and has been suggested to be involved in the remodeling processes associated with atherosclerosis and plaque rupture." (PMID 35449607, 2022).
atherosclerosis (continued). "Luseogliflozin regulates the expression of multiple mRNA, including MMP9, and inhibits the progression of atherosclerosis in diabetic APOE-deficient mice." (PMID 35677689, 2022). "MMP-9 controls the degradation and remodeling of extracellular matrix and is involved in the formation of atherosclerosis, increasing the risk of plaque rupture." (PMID 35399851, 2022). "MMP-9, also known as gelatinase B or type IV collagenase, has been linked to atherosclerosis development." (PMID 34829801, 2021). "In human atherosclerosis, a microbiome with pathogenic archaea is associated with increased free radical formation, MMP9 release, and increased plaque vulnerability, leading to acute myocardial infarction with a worse prognosis." (PMID 34422924, 2021). "MMP-9 has been associated with the progression of atherosclerosis and plaque rupture, and the development of vascular events in carotid atherosclerotic disease." (PMID 34067481, 2021). "Specifically, MMP9 is implicated in the pathogenesis of atherosclerosis, as its ablation protects apolipoprotein E-deficient mice against atherosclerosis." (PMID 34829669, 2021). "Visfatin, which is the common pathogenic factors of psoriasis and atherosclerosis, induces the increased expression of MMP9 in the carotid plaques in an indirect way." (PMID 34122426, 2021). "MMP-9 is involved in all stages of atherosclerosis and MMP-9 deletion is associated with reduced plaque size, macrophage content and collagen deposition in aortic lesions of ApoE-/- mice." (PMID 34797846, 2021). "LPA and MMP9 have been recognized as risk factors, per se, to atherosclerosis development via lipid metabolism, inflammation and oxidative stress." (PMID 32218930, 2020). "Atherosclerotic plaque formation is associated with hypertension-induced atherosclerosis and increased levels of MMP-9 mRNA." (PMID 32486345, 2020). "Considering that the aberrant cell functions of VSMCs such as proliferation, migration, and apoptosis are associated with the development of atherosclerosis, we investigated the biological effects of miR-491-5p and MMP-9 on VSMCs." (PMID 33313408, 2020). "Enhanced expression of MMP-9 in VSMCs can be caused by angiotensin II (Ang II) that participates in atherosclerosis by NF-κB pathways and angiotensin type 1 receptor." (PMID 32486345, 2020). "Whereas all MMPs are likely risk factors for atherosclerosis and cardiac dysfunction, a more specific mechanism of damage has been postulated for MMP-9 and TIMP-1." (PMID 31963569, 2020). "The involvement of MMP-9 in atherosclerotic incidents is a matter of ongoing debate, and more and more researchers have focused on the study of the effects and molecular mechanisms underlying MMP-9 in atherosclerosis." (PMID 33313408, 2020). "MMP9 proteins are also implicated in several stages of atherosclerosis involving leukocyte adhesion, cell migration, and matrix degradation." (PMID 31935243, 2020). "Matrix metalloproteinase-9 also plays a critical role in the progression of atherosclerosis, loss of MMP-9 reduced the atherosclerotic burden throughout the aorta and impaired macrophage infiltration and collagen deposition." (PMID 30142970, 2018). "In one report, MMP-9 deficiency protected against cholesterol diet-induced atherosclerosis, but in another, MMP-9 inactivation increased the atherosclerotic plaque growth and progression." (PMID 30413026, 2018). "In particular, metalloproteinase-9 (MMP-9, gelatinase B, or type IV collagenase), has been implicated in the pathogenesis of atherosclerosis." (PMID 28166283, 2017). "Nucleotide polymorphisms of the MMP-9 gene are associated with the presence and severity of atherosclerosis; and increased circulating levels of MMP-9 have been identified in type 2 diabetes patients with coronary artery disease." (PMID 28166283, 2017). "While this paper was being written, it was reported that Mmp-9-deficient mice had an abnormal cholesterol metabolism, leading to atherosclerosis." (PMID 28757161, 2017).